AXL (AXL receptor tyrosine kinase)
Diseases named in the same sentence as AXL in open-access papers (continued):
Sharing a sentence is not in itself a finding about the gene and the disease.
vascular disorder (1 paper, 2019). A general term used to describe any disease affecting blood vessels]. "AXL is a receptor tyrosine kinase that has been related to kidney and vascular disorders." (PMID 31181097, 2019).
AXL also shares sentences with these, for which no sentence is quoted: microcephaly (5 papers); multiple myeloma (5); myxofibrosarcoma (3); nonalcoholic steatohepatitis (3); prostate tumor (3); acute lymphoblastic leukemia (2); chronic kidney disease (2); colorectal adenoma (2); congenital malformations (2); cutaneous squamous cell carcinoma (2); immune disorders (2); inflammatory bowel disease (2); non-alcoholic fatty liver disease (2); portal hypertension (2); skin cancer (2); soft tissue sarcoma (2); acute promyelocytic leukemia (1); acute respiratory distress syndrome (1); amyloidosis (1); amyotrophic lateral sclerosis (1); biphasic mesothelioma (1); blood cancers (1); cancers of the gastrointestinal tract (1); childhood cancers (1); chordoma (1); chronic liver failure (1); chronic periodontitis (1); colon adenocarcinoma (1); diffuse large B-cell lymphoma (1); diffuse malignant mesothelioma (1).
A further 62 diseases each share a sentence with AXL in 1 paper.